DAPK1 (death associated protein kinase 1)
Diseases named in the same sentence as DAPK1 in open-access papers (continued):
Sharing a sentence is not in itself a finding about the gene and the disease.
ischemic stroke (19 papers, 2017 to 2025). A stroke disorder caused by obstruction of blood flow to the brain, due to thrombotic (local blood clot formation) or embolic (due to a blood clot or other material traveling from another site) event. "For example, miR‐124 can target DAPK1 to inhibit neuronal cell death caused by ischemic stroke in mice, and miR‐124 can regulate the expression of DAPK1 and affect cell apoptosis in Parkinson's disease." (PMID 39833100, 2025). "The Ca2+/CaM-dependent Ser/Thr kinase DAPK1 has been implicated in neuronal loss in ischemic stroke, TBI and neurodegenerative diseases such as AD." (PMID 38195518, 2024). "Our recent study provides robust evidence supporting a causative role of Tau phosphorylation by DAPK1 in mediating dendritic spine injuries in ischemic stroke." (PMID 27447806, 2017). "Moreover, DAPK1 mediates neuronal death caused by ischemic stroke via phosphorylation of the NR2B subunit of the NMDAR." (PMID 33841091, 2021). "We showed that the activated DAPK1 phosphorylated Tau at Ser262 results in the possible formation of indissoluble tau and accumulation in the dendritic spines, which was the possible cause of synaptic damage in ischemic stroke." (PMID 27447806, 2017). "Moreover, a membrane-permeable blocking peptide (TAT-R1D), which targets the DAPK1-tau binding peptide, blocks the formation of the complex and tau phosphorylation, significantly reducing the infarct area and neuronal loss induced by ischemic stroke." (PMID 31248062, 2019). "DAPK1 is known to mediate apoptosis and autophagy, processes that are critical in the context of ischemic stroke." (PMID 40918124, 2025). "MiR-124 binds to the 3′ UTR of DAPK1 mRNA and affects the translation of DAPK1 in ischemic stroke models." (PMID 38195518, 2024). "It should be mentioned that the transient activation of DAPK1 is required for LTD induction under physiological conditions, which differs from the sustained upregulation of DAPK1 in ischemic stroke or AD." (PMID 38195518, 2024). "Dysregulation of DAPK1 has been shown to contribute to various neurological diseases including AD, ischemic stroke and Parkinson’s disease (PD)." (PMID 38195518, 2024). "Similar to PSD95, the interruption of the GluN2B-DAPK1 interaction via an interfering peptide or via the genetic deletion of DAPK1 provided protection against brain damage in ischemic stroke." (PMID 37631001, 2023). "DAPK1 has been shown to be involved in various neurodegenerative diseases, such as AD, ischemic stroke, PD and epilepsy." (PMID 35742817, 2022). "In this study, we identified a novel miR-124/DAPK1 pathway in neuronal death and damage following ischemic stroke." (PMID 33841091, 2021). "The high selectivity of C6 for DAPK1 allows it to potentially contribute to the treatment of ischemic stroke." (PMID 31248062, 2019). "A specific small-molecule inhibitor of DAPK1 (IC50 = 13 μM) is an alkylated 3-amino-6-phenylpyridazine that is known to significantly attenuate brain damage after ischemic stroke." (PMID 31248062, 2019). "How this presynaptic DAPK1-caytaxin interaction affects synaptic transmission and neuronal fate after ischemic stroke needs further exploration." (PMID 27447806, 2017). "The dysregulation of DAPK1 in neuronal cell death was first demonstrated in ischemic stroke." (PMID 38195518, 2024). "Targeting DAPK1-related pro-death signals could be considered as a promising therapeutic approach in salvageable brain tissue after ischemic stroke." (PMID 38166912, 2024).
ischemic stroke (continued). "DAPK1 is a potential molecular target for neuronal cell death, and certain inhibitors of DAPK1 have indicated the potential of new therapeutic strategies for treating neurodegenerative diseases such as ischemic stroke and AD." (PMID 31248062, 2019). "In addition, increased DAPK1 activity has also been detected in an in vivo model of ischemic stroke." (PMID 31248062, 2019). "Interestingly, the interaction between DAPK1 and Caytaxin also reciprocally inhibits the presynaptic DAPK1 activity and protects neurons against the ischemic stroke-induced apoptosis, representing an early protective mechanism by which neurons antagonize ischemic brain injuries." (PMID 38195518, 2024). "Interestingly, DAPK1 is able to interact with the tau protein through its kinase domain, further leading to tau phosphorylation at Ser262, promoting dendritic spine damage and neuronal death in ischemic stroke mice." (PMID 38195518, 2024). "Furthermore, death-associated protein kinase 1 (DAPK1) can interact directly with the CTD of GluN2B, which may be a therapeutic target for ischemic stroke." (PMID 37153659, 2023). "Consequently, inhibition of tau phosphorylation by DAPK1 may be a potential therapeutic target for ischemic stroke." (PMID 31248062, 2019). "Targeting DAPK1-related pro-death signals in both presynaptic and postsynaptic neurons may eventually lead us to improved methods to treat salvageable brain tissues after ischemic stroke." (PMID 27447806, 2017). "Activated DAPK1 directly interacts with the NMDA receptor GluN2B protein complex and phosphorylates the GluN2B subunit at Ser1303 in the cortex of ischemic stroke mice." (PMID 31248062, 2019). "Importantly, the DAPK1-induced Ser1303 phosphorylation of the NMDAR GluN2B subunit, which was originally reported to be detrimental in ischemic stroke, has essential physiological functions in modulating LTP and LTD." (PMID 38195518, 2024). "DAPK1 is activated through its dephosphorylation after focal cerebral ischemia in a transient middle cerebral artery occlusion (MCAO) model, which is widely used to study therapies for ischemic stroke." (PMID 31248062, 2019). "Additionally, the upregulation of DAPK1 by Aβ oligomers leads to Ca2+ overload and excitotoxicity in the SH-SY5Y cell line via phosphorylation of the Ser1303 residue of the NMDAR GluN2B subunit, resembling the effect observed in an ischemic stroke mouse model." (PMID 38195518, 2024).
ovarian carcinoma (18 papers, 2006 to 2025). A malignant neoplasm originating from the surface ovarian epithelium. "ATF6-associated autophagy participates in ovarian cancer cell chemoresistance, death-associated protein kinase 1 (DAPK1)-related chronic lymphocytic leukemia cell death, and cancer-associated fibroblast (CAF) activation in lung adenocarcinoma progression." (PMID 37456776, 2023). "Further dependencies were identified for this complex within specific histotypes including the uridine-cytidine kinase gene UCK2 in ovarian cancer models and the death-associated protein kinase gene DAPK1 in esophageal cancer models." (PMID 26947069, 2016). "Our data also demonstrate that DAPK1 and TAp63 levels could be used as diagnostic or determining factors of drug resistance before starting repeated chemotherapy against ovarian cancer." (PMID 31336860, 2019). "The expression of PLK1, a key regulator of cell cycle progression and a marker of cellular proliferation, was inversely correlated with the vector-prone increase in DAPK1 re-expression, supporting an anti-proliferative role of DAPK1 in ovarian cancer." (PMID 40563561, 2025). "Here, the vector-based expression of DAPK1-clone 6 has been shown to trigger apoptosis in ovarian cancer lines and sensitize cancer cells to chemotherapeutics, the mainstays of ovarian cancer therapy." (PMID 40563561, 2025). "Given the relatively long open reading frame of DAPK1 (4,290 base pairs), we generated a series of constructs containing different functional domains of DAPK1 and assessed their anti‐tumor efficacy in ovarian cancer cells." (PMID 40391786, 2025). "Our observations provide critical mechanistic insights into how DAPK1 influences ovarian cancer progression." (PMID 40563561, 2025). "Previous experiments about the impact of vector-based expression on the response to standard therapeutics had demonstrated that the reactivation of DAPK1 sensitizes ovarian cancer cells to Paclitaxel and Cisplatin." (PMID 40563561, 2025). "Higher level of miR-191 in ovarian cancer patient samples compared with controls was verified, and miR-191 was confirmed to directly target DAPK1 and regulate its expression using luciferase assay." (PMID 34422899, 2021). "Death-associated protein kinase 1 (DAPK1) expression induced by diverse death stimuli mediates apoptotic activity in various cancers, including ovarian cancer." (PMID 31336860, 2019). "Recently, we revealed direct evidence that DAPk1 is a major regulator of IFN-γ-induced apoptotic cell death in human ovarian carcinoma cells." (PMID 25568671, 2014). "In this study, we could corroborate strong DAPK1 expression in the ovarian cancer cell line SKOV-3 (low-grade serous ovarian cancer)." (PMID 40563561, 2025). "Truncated, short forms of DAPK1, which may allow for improved uptake, translation, and stability in human cells, were also tested for their ability to sensitize ovarian cancer cells to Paclitaxel treatment." (PMID 40563561, 2025). "Considering the upregulated promoter methylation of DAPK1 and its prognostic power in the early stages of the disease, we wondered whether DAPK1 reactivation might have anti-proliferative potential in ovarian cancer." (PMID 40563561, 2025).
ovarian carcinoma (continued). "We identified aberrant DAPK1 expression in ovarian cancer and sought to investigate whether restoring DAPK1 function could serve as a potential therapeutic strategy." (PMID 40391786, 2025). "In ovarian cancer, knockdown of DAPK1 could weaken its response to TNF-αinduced cell death in CRL-7566 cells." (PMID 34422899, 2021). "In addition, sequential treatment with gliotoxin followed by paclitaxel activated the DAPK1-mediated TAp63 signaling pathway to induce autophagic cell death in paclitaxel-resistant ovarian cancer cells." (PMID 31336860, 2019). "In addition, ovarian cancer TCGA patients with low stages (I and II) and a high methylation of DAPK1 at the cg22571217 site displayed poor overall survival (log-rank p = 0.007), supporting the role of the epigenetic regulation of DAPK1 in ovarian cancer patients." (PMID 40563561, 2025). "Due to the relevance of Carboplatin or Cisplatin combined with Paclitaxel as part of the standard chemotherapy employed to treat ovarian cancer patients, we also determined the sensitivity of OVCAR-8 cells expressing truncated DAPK1 to Cisplatin." (PMID 40563561, 2025). "Herein, the promoter methylation of seven ovarian cancer-specific genes (RASSF1A, DAPK1, SOX1, HOXA9, HIC1, SPARC, and SFRP1) was analyzed quantitatively in 120 tissue samples by MethyLight assay." (PMID 34778370, 2021). "To explore the significance of DAPK1 expression in ovarian cancer patients, we used a database including 1436 patient samples with available progression-free survival (PFS) times to evaluate the prognostic potential of DAPK1." (PMID 40563561, 2025). "To this end, we evaluated the effects of the re-expression of wild-type (wt), full-length, Flag-tagged DAPK1 on cell viability using high-grade and non-high-grade ovarian cancer cell lines." (PMID 40563561, 2025). "Thus, we added DAPK1, a new gene, to the list of hypermethylated tumor suppressors, including BRCA1 and RASSF1A, that are prognosis-relevant in ovarian cancer." (PMID 40563561, 2025). "In addition, our findings showed that the methylation levels of candidate genes (HIC1, HOXA9, SOX1, DAPK1, RASSF1A, SFRP1, and SPARC) were significantly elevated in patients with ovarian cancer and was highly cancer-specific, which is in concord with the previously published reports." (PMID 34778370, 2021). "However, the expression and specific role of DAPK1 in ovarian and paclitaxel-resistant ovarian cancer cells after treatment with gliotoxin have not been studied." (PMID 31336860, 2019). "In addition, DAPK1 gene silencing using siRNA prevented the cleavage of caspase-9, caspase-3, and PARP as well as the depolarization of mitochondria membranes induced by treating paclitaxel-resistant ovarian cancer cells with gliotoxin followed by paclitaxel." (PMID 31336860, 2019).
Cerebral ischemia (13 papers, 2013 to 2024). Restriction of arterial blood supply to the brain associated with insufficient oxygenation to support the metabolic requirements of the tissue. "DAPK1-mediated tau phosphorylation is involved in spinal cord injury and neuronal cell loss in cerebral ischemia." (PMID 31248062, 2019). "GluN2B promotes cell death following cerebral ischemia, activating many pro-death signaling molecules, such as neuronal nitric oxide synthase (nNOS) and death-associated protein kinase 1 (DAPK1)." (PMID 28174519, 2017). "Dysregulation of the NMDAR following cerebral ischemia in adult mice was recently linked to recruitment of DAPk1 into the NR2BR protein complex." (PMID 23880846, 2013). "Thus, research has indicated that cerebral ischemia triggers the activation of death-associated protein kinase 1 and suggests that this contributes to the increase in cis-phosphorylated tau protein levels after cerebral ischemia." (PMID 38542064, 2024). "In addition, treatment of rats with a small-molecule DAPk1 inhibitor even 6 hours after cerebral ischemia attenuated the loss of brain tissue, measured one week later." (PMID 23880846, 2013). "A quantitative proteomic analysis revealed DAPK1 as the most prevalent protein recruited to the cytoplasmic tail of glutamate receptor during cerebral ischemia." (PMID 38166912, 2024). "During cerebral ischemia, DAPK1 is dephosphorylated and then interacts and phosphorylates the CTD-NR2B to enhance the inflow of Ca2+ into the neuron, further exacerbating excitotoxicity in a vicious circle." (PMID 33265962, 2020). "Therefore, increasing the knowledge of DAPK1 interactions of the neuron in ischemic and ischemic-like conditions is a sine qua non condition to broaden the array of molecules susceptible to further functional studies as a strategy in the search for therapies in cerebral ischemia." (PMID 33265962, 2020). "DAPK1 mRNA expression is increased following cerebral ischemia, and the function of DAPK1 is dependent on the catalytic activity of the kinase domain." (PMID 31248062, 2019). "With the evidence that DAPK1-mediates injury in cerebral ischemia and the ability of bioavailable DAPK1 inhibitors to rescue neuronal death, DAPK1 has emerged as an important drug-discovery target for brain disorders." (PMID 24755839, 2014). "With the evidence of DAPk1-mediated injury in cerebral ischemia and the ability of bioavailable DAPk inhibitors to rescue neuronal death, DAPk1 has emerged as an important drug-discovery target for brain disorders." (PMID 23880846, 2013). "Cerebral ischemia may promote the formation of the GluN2B/DAPK1 complex, activate DAPK1-dependent phosphorylation of GluN2B, and enhance the NMDAR channel conductance, leading to neuronal death." (PMID 37153659, 2023). "Knockdown of LncRNA AK038897 could protect against cerebral ischemia/reperfusion injury by regulating miR-26a-5 targeting of DAPK1." (PMID 32138732, 2020). "It is known that cerebral ischemia induces overexcitation of the NMDA receptor, causing excessive Ca2+ flow into the cytoplasm and activates not only CaM but also the calcineurin phosphatase (CaN) and dephosphorylates DAPK1 in Ser308." (PMID 27447806, 2017). "DAPK1 knockout mice have a markedly reduced infarct volume of and improved neurological function after MCAO-induced cerebral ischemia." (PMID 31248062, 2019).
Cerebral ischemia (continued). "Although DRP1 and ZIPk are not reported to be directly regulated in response to cerebral ischemia, DAPk1 mRNA levels are increased in response to neonatal hypoxia-ischemia in vivo." (PMID 23880846, 2013).
neuroblastoma (13 papers, 2004 to 2023). Neuroblastoma (NB) is the most common solid, extracranial childhood tumor. "Mitochondrial toxins, such as rotenone, and carbonyl cyanide m-chlorophenylhydrazone (CCCP), which is an uncoupler of mitochondrial oxidative phosphorylation induce loss of membrane potential and mitochondrial swelling leading to cell death via DAPK1 activation in neuroblastoma cells." (PMID 34389795, 2021).
chronic lymphocytic leukemia (12 papers, 2011 to 2024). "HOXB7 gene in chronic lymphocytic leukemia is hypermethylated and represses Death-Associated Protein Kinase 1 gene expression." (PMID 33225883, 2020). "In 2013 it was discovered that ASE, at the death-associated protein kinase 1 (DAPK1) gene locus, was potentially predisposed to chronic lymphocytic leukemia (CLL) using a single-nucleotide primer extension (SNuPE) and MALDI-TOF mass spectrometry." (PMID 30538721, 2018). "Heterogeneous methylation of DAPK1 promoter has been shown previously in patients with chronic lymphocytic leukemia or diffuse large B-cell lymphoma." (PMID 26370119, 2015). "Hypermethylation of DAPK1 is the most frequent molecular alteration identified in immunodeficiency-related lymphomas, and was detected in almost all cases of chronic lymphocytic leukemia." (PMID 25986046, 2015). "We previously reported a rare germline variant (c.1-6531) that resulted in allele–specific expression (ASE) of death-associated protein kinase 1 (DAPK1) and predisposition to chronic lymphocytic leukemia (CLL)." (PMID 23383130, 2013). "In chronic lymphocytic leukemia (CLL), TSGs including DAPK1, SFRP1 or SFRP2 have been shown to be aberrantly methylated (hypermethylated)." (PMID 24559316, 2014). "Of note, the DNA hypermethylation in TSGs, such as DAPK1, ID4, SFRP1, TWIST2 and ZAP70, has been identified to play a role in the pathogenesis or prognosis of chronic lymphocytic leukemia (CLL)." (PMID 24373626, 2013).